GSDMD (gasdermin D)
Diseases named in the same sentence as GSDMD in open-access papers (continued):
Sharing a sentence is not in itself a finding about the gene and the disease.
tumor (continued). "Similarly, pyroptosis induced by gasdermin D (GSDMD) is also an important form of cell death related to the mechanism of chemotherapy drugs killing tumor cells." (PMID 37153795, 2023). "Moreover, the nanoinhibitor combined with heat induced pyroptosis of tumor cells by the caspase 1/GSDMD pathway." (PMID 37316830, 2023). "Additionally, tumor cell pyroptosis induced by chemotherapeutic drugs or macrophage-derived tumor necrosis factor α (TNF-α) can occur through the caspase-8/GSDMD/GSDME/GSDMC pathway." (PMID 38264354, 2023). "Active caspase-1 directly cleaves GSDMD and induces pyroptosis in tumor cells." (PMID 35673561, 2022). "The immunological properties of GSDMD-NT-mediated pyroptotic tumor cells were analyzed in vitro." (PMID 36189310, 2022). "Accordingly, inducing pyroptosis of NSCLC cells through the NLRP3/caspase-1/GSDMD pathway may be potential targets for inhibiting the tumor progression of NSCLC." (PMID 36467499, 2022). "The expression of GSDMD in tumours remains to be further investigated." (PMID 35289335, 2022). "In addition, GSDMD gene expression in cancer patients is a positive predictor of local tumor recurrence." (PMID 36120543, 2022). "Therefore, the clinical use of a specific inhibitor of gasdermin D for the activation of gasdermin E in tumor cells, and the blocking of gasdermin D, can prevent the occurrence of CRS while exerting CAR-T efficacy, thus improving the safety of treatment." (PMID 36038533, 2022). "GSDMD could enhance tumor proliferation in non−small cell lung cancer and promote the invasion capacity of adenoid cystic carcinoma." (PMID 36505474, 2022). "Furthermore, the expression of GSDMD-NT in tumor tissue was confirmed by RT-qPCR after the doxy induction." (PMID 36189310, 2022). "Although the repeated freeze-thaw cell lysate (FT) also inhibited the growth of tumors as compared to the unvaccinated control (the mice only received PBS), the GSDMD-NT-expressing tumor cells presented a better effect, indicating that the pyroptotic cells produced stronger antitumor immunity." (PMID 36189310, 2022). "Results showed that GSDMD expression levels increased with tumor grade in LICH." (PMID 35922531, 2022). "The observation that GSDMD is highly expressed in tumours indicates that GSDMD could have functions other than pyroptosis." (PMID 35289335, 2022). "The expression of GSDMD was significantly upregulated in non-small cell lung cancer (NSCLC), and higher GSDMD expression is associated with invasive features, including more advanced tumor-node-metastasis stages and larger tumor sizes." (PMID 35659304, 2022). "The increased DC maturation in VNP-GD/EI-NP@Gel was probably attributed to the enhanced tumor antigen release after tumor cell pyroptosis mediated by the combination of tumor-selective intracellular delivery of GSDMD by VNP and membrane repair inhibition by EI-NP." (PMID 36280674, 2022). "In summary, we developed a hydrogel-based delivery system serving as a local reservoir to sustainedly release VNP-GD and EI-NP for enhanced programmed tumor cell death by integrating VNP-activated GSDMD-dependent tumor pyroptosis and inhibition of ESCRT III-mediated plasma membrane repair." (PMID 36280674, 2022). "The results showed that the local inoculation of GSDMD-NT gene modified tumor cells with the induction of pyroptosis by drinking with doxy water significantly suppressed the growth of fully established tumors and in some cases, led to complete eradication of the tumor." (PMID 36189310, 2022). "To determine whether GSDMD-induced tumor-cell pyroptosis augments tumor immunity as well, we first evaluated the correlation of GSDMD mRNA level with the abundance and cytotoxicity of T lymphocytes in TME across TCGA tumor types." (PMID 36323669, 2022).
tumor (continued). "The correlation between GSDMD gene expression and various clinical, laboratory, and pathological parameters revealed a strong positive correlation with GSDMD protein expression in tissue samples, tumor stage, group, and lymph node involvement, as well as a weak positive correlation with tumor grade." (PMID 36120543, 2022). "Jianwei Gao and colleagues also found that increased GSDMD expression levels may increase the tumor size, promote more advanced tumor-node-metastasis stages, and affect survival rates." (PMID 36482419, 2022). "In addition, in previous studies, benzimidazole was found to trigger GBM pyroptosis via the NF‐κB/NLRP3/GSDMD pathway to achieve anti‐tumour effects." (PMID 35083859, 2022). "In our previous study, we found that CuB at 100 nM could induce pyroptosis in A549 cells through TLR4/NLRP3/GSDMD signaling pathways, and administration with CuB at 0.25 mg/kg, 0.5 mg/kg and 0.75 mg/kg inhibited the tumor growth in NSCLC xenograft mice model." (PMID 35183200, 2022). "GSDMD-NT expression induces tumor cell pyroptosis and ICD mediator release." (PMID 36189310, 2022). "Also found that low expression or inhibited expression of gasdermin D (GSDMD) can promote tumour cell proliferation in GC." (PMID 35923703, 2022). "Whether anti-tumor immune response also leads to GSDMD cleavage to elicit pyroptosis in tumor cells is largely unknown." (PMID 36323669, 2022). "Given the potent immunostimulatory effects of GSDMD-mediated pyroptosis, we, therefore speculated that transcriptional induction of Gsdmd may have an important function in tumor-cell pyroptosis induction and immune elimination of Mll4−/− tumors." (PMID 36323669, 2022). "We found levels of both full-length and N-terminal fragment of GSDMD are elevated in Mll3−/− and Mll4−/− bulk tumors, indicating that Mll3 and Mll4 deletion induces GSDMD expression and could transcriptionally prime tumor cells for pyroptosis." (PMID 36323669, 2022). "TUNEL staining of transplanted tumour tissues indicated that luteolin might cause apoptosis, while NLRP3/GSDMD colocalization staining indicated that luteolin could also cause pyroptosis." (PMID 36105214, 2022). "GSDMD significantly inhibits the growth of tumours in vivo and in vitro." (PMID 35896522, 2022). "In the present study, NLRP3/caspase-1/GSDMD pyroptosis pathway was involved in the DDP-induced anti-tumor effect of TNBC in vitro and in vivo, providing evidence that DDP might induce pyroptosis in TNBC." (PMID 34326697, 2021). "GSDMD, expressed by tumor cells or by cells from the TME, might therefore also be linked to positive effects in some circumstances." (PMID 34490126, 2021). "Furthermore, RNA-interference mediated knockdown of GSDMD in tumor NSCLC cell lines attenuates tumor proliferation in vitro, as well as in vivo in xenografted immunodeficient mice." (PMID 34490126, 2021). "Downstream of inflammasome and GSDMD activation, IL-1β and IL-18 can also have a beneficial effect as they play a pivotal role in the activation of dendritic and natural killer (NK) cells, respectively, and can, thereby, promote anti-tumor immune responses." (PMID 34490126, 2021). "Select chemotherapeutic agents have also been described to activate caspase-8-dependent GSDMC activation in tumor cells, or GSDMD activation in myeloid cells, however, whether myeloid GSDMD activation promotes or dampens tumor growth in vivo remains unclear." (PMID 33868312, 2021). "However, it has been reported that GSDMA, GSDMC, and GSDMD have the effect of inhibiting tumor proliferation." (PMID 34778452, 2021). "Similarly, human CD8+ T cells upregulated GSDMD following their activation, and in LUAD and LUSC tissue samples, high levels of GSDMD protein were seen in tumor-infiltrating lymphocytes (TILs)." (PMID 34429144, 2021). "This suggested that GSDMD expression could limit tumor cell intrinsic proliferation in this type of tumor and sensitize the cells to a pyroptotic cell death." (PMID 34490126, 2021).
tumor (continued). "Hydrogen exerts a biphasic effect on cancer by promoting tumor cell death and protecting normal cells, which might initiate GSDMD pathway-mediated pyroptosis." (PMID 31924176, 2020). "Furthermore, knockdown of GSDMD attenuates tumor proliferation by promoting apoptosis and inhibiting epidermal growth factor receptor (EGFR)/Akt signaling axis." (PMID 33613533, 2020). "Furthermore, overexpression of GSDMD markedly overcame the inhibitory effect of CD147 peptide on tumor proliferation." (PMID 32149134, 2020). "DCBLD2 and GSDMD have considerable tumour-specific effects, but their roles in PDAC development remain unclear." (PMID 32958051, 2020). "Compared with normal nude mice, the tumor volume in nude mice with low-level GSDMD was larger after the implantation of GC cells, suggesting that the GSDMD level may be related to the GC occurrence." (PMID 31501419, 2019). "GSDMD, a key regulator of pyroptosis, is widely expressed in both non-tumor and tumor cells, playing a role in mediating inflammatory damage in non-tumor diseases and contributing to diverse pathological processes in tumor diseases, including tumor progression and suppression." (PMID 39994107, 2025). "While activation of pyroptosis-related genes (e.g., CASP1, GSDMD) enhances inflammation and attracts immune cells, it may paradoxically promote tumor progression by allowing HCC cells to escape immune surveillance through modulation of apoptosis-inducing factors." (PMID 40018411, 2025). "However, some tumor cells can escape the induction of pyroptosis and promote tumor development through different pathways, such as regulating the inflammasome signaling pathway and regulating the expression of Gasdermin D (GSDMD) protein." (PMID 39834603, 2025). "Indeed, tumor cells transfected with siSNRPE exhibited elevated level of cleaved-GSDMD." (PMID 40386046, 2025). "Moreover, targeting GSDMD-mediated pyroptosis may offer a novel approach to harnessing the immune system for anti-tumor immunity." (PMID 40491921, 2025). "By fusing a gasdermin D mutant to a mitochondrial-targeting peptide, they harnessed mitochondrial inner membrane cardiolipin toxicity to trigger mitophagy-mediated tumor cell death, which markedly suppressed tumor growth in xenograft models of EIF4G2+/PTBP1+ adenocarcinomas." (PMID 41226581, 2025). "Neither tumor growth nor tumor weight were influenced by the deficiency in GSDMD." (PMID 39224600, 2024). "DMB substantially inhibited tumor growth in wild-type mice, but not in GSDMD-deficient models." (PMID 39587093, 2024). "Thus, intratumoral GSDMD expression may differently impact antitumor immunity depending on the tumor type and context." (PMID 39224600, 2024). "However, GSDMD can induce invasion and tumor progression in lung cancer." (PMID 38221934, 2024). "Therefore, GSDMD-mediated pyroptosis is a double-edged sword for tumor development, and the detailed mechanisms of whether it promotes or inhibits tumor survival in different tissues and genetic backgrounds need further exploration." (PMID 37275856, 2023). "In addition, overexpression of GSDMD also promotes tumor proliferation in bladder cancer." (PMID 37275856, 2023). "Moreover, GSDMD expression levels were correlated with tumor size and stage in NSCLC." (PMID 38066523, 2023). "The GSDMD-mediated pyroptosis might happen during conventional anti-tumor therapy." (PMID 36932407, 2023). "Conversely, silencing GSDMD could inhibit transplanted tumor growth in mice." (PMID 38011122, 2023). "Thus mediation of tumor cell death by inflammasomes is mainly achieved by GSDMD-induced pyroptosis." (PMID 36932407, 2023). "Moreover, anti-PD-1 treatment further increases the abundance and promotes the cytotoxic potential of CD8+ T cells in tumors ectopically expressing wild-type GSDMD, suggesting PD-1 blockade and GSDMD can synergize with each other to potentiate anti-tumor efficiency of cytotoxic T lymphocytes." (PMID 36323669, 2022).
tumor (continued). "GSDMD protein cage-conjugated VNP bacteria (designated VNP-GD) could effectively shuttle GSDMD to the cytoplasm of the tumor cells, which will subsequently release GSDMD intracellularly upon the activation of elevated GSH concentration to trigger tumor cell pyroptosis." (PMID 36280674, 2022). "Therefore, in the envisioned strategy, Adriouch team aims to use viral vectors, akin to AAV, to induce ICD intratumorally by expressing active truncated/mutated forms of GSDMD, GSDME or MLKL, thus bypassing tumor resistance to the induction of pyroptosis or necroptosis." (PMID 35883457, 2022). "The suppressive effects of exogenous GSDMD expression on tumor progression were not noticed when B16 cells were implanted in immune-deficient Rag1−/− mice, highlighting the requirement of an intact immune system for tumor suppression by GSDMD." (PMID 36323669, 2022). "Moreover, the abundant flagella of VNP could activate the caspase 1 to transform the delivered GSDMD proteins into the active form for triggering tumor cell pyroptosis." (PMID 36280674, 2022). "Therefore, in this study, the remaining GSDMD-NT after pyroptosis and lysis of GSDMD-NT-expressing tumor cells did not cause damage to nearby tissues and cells." (PMID 36189310, 2022). "Next, the genetically modified tumor cells were inoculated into mice to test whether artificial control of GSDMD-NT expression and pyroptosis occurrence induced by supplementing their drinking water with doxy could abolish the development of tumors from the inoculated cells." (PMID 36189310, 2022). "Due to the intrinsic heterogeneity of tumor cells, the degree of epigenetic derepression of GSDMD after Mll4 ablation may vary among different single cells, leading to the variable abundance of GSDMD in individual Mll4-ablated single cells." (PMID 36323669, 2022). "It is difficult to control the number of tumor cells undergoing pyroptosis using chemotherapeutic drugs or other pyrolysis inducers, while the approach reported here can control the intensity of pyroptosis by adjusting the number of modified GSDMD-NT tumor cells." (PMID 36189310, 2022). "Thus, our data uncovered a novel mechanism that DDP induced pyroptosis via activation of MEG3/NLRP3/caspase-1/GSDMD pathway in TNBC to exert anti-tumor effects, which may help to develop new strategies for the therapeutic interventions in TNBC." (PMID 34326697, 2021). "However, downregulation of GSDMD expression was found to promote S/G2 cell cycle transition, which indicated that GSDMD may serve as a tumor suppressor in gastrointestinal cancers." (PMID 34712271, 2021). "Finally, crosstalk with oncogenic pathways could override GSDMD’s tumor-suppressive potential." (PMID 40491921, 2025). "In vivo, LHA significantly reduced tumor growth and altered tumor histopathology in a PDAC xenograft model, along with downregulated eEF2K and upregulated pyroptosis executors (GSDMD/GSDME)." (PMID 40567376, 2025). "Ca2+ induces tumor cell pyroptosis primarily through the GSDME pathway, whereas Zn2+ induces tumor cell pyroptosis primarily through the GSDMD pathway." (PMID 40486836, 2025). "Additionally, the level of GSDMD expression may influence the invasiveness of tumor cells." (PMID 40008397, 2025). "In mouse models of NSCLC, cucurbitacin B effectively inhibits tumor growth and shows superior anti-tumor effects compared to standard treatments, underscoring its potential as a targeted therapy through the TLR4/NLRP3/GSDMD signaling axis." (PMID 40149884, 2025). "Some microRNAs can affect the activation of pyroptosis by regulating the expression of pyroptosis-related proteins, thereby inhibiting tumor growth and metastasis, such as NLRP3 inflammasomes and GSDMD." (PMID 39834603, 2025). "Pyroptosis induced by caspase-4/GSDMD can also promote the release of inflammatory factors such as IL-1β and IL-18, as well as recruit CD8+ T cell infiltration, thereby activating anti-tumor immunity." (PMID 39062587, 2024).
tumor (continued). "ATP from the pyroptosing tumor cells subsequently activates the NLRP3 inflammasome in macrophages, resulting in caspase-1 activation and downstream GSDMD and IL-1β processing and release." (PMID 38391959, 2024). "In conclusion, the findings of this study suggest that the tumour inflammatory environment induced by hypoxia promotes IL37 expression via NLRP3 inflammasome activation, and IL37 release through NLRP3/GSDMD." (PMID 39500733, 2024). "In present study, compared with tumor model group, the expression of NLRP3, caspase 1, GSDMD and the level of IL-1β and IL-18 in XRZYBXD high dose group were increased." (PMID 40046008, 2024). "GSDMA, GSDMB, GSDMD, and GSDME displayed significantly higher expression in tumor stage 2 and 3 than in normal tissues." (PMID 39607202, 2024). "In tumors exhibiting immune cell infiltration, a high expression of GSDMD and GSDME often accompanies this phenomenon, indicating tumor pyroptosis and the immune response exhibit a mutually reinforcing positive feedback mechanism." (PMID 39069522, 2024). "In vivo, okanin reduced tumor growth and involved pyroptosis-related markers such as CASP1, GSDMC, GSDMD, and GSDME." (PMID 39335166, 2024). "To explore the biological functions of miR-221-5p in CRC, we performed RT-PCR and found that miR-221-5p, together with GSDMD, was upregulated in CRC tumor tissues." (PMID 39439418, 2024). "We found that the expression of GSDMs was significantly higher with higher tumor stage, which was particularly evident in GSDMB, GSDMD, and DFNB59." (PMID 38434972, 2024). "Additionally, GSDMD-mediated mitochondrial damage is considered a key molecular mechanism in the early stages of pyroptosis, playing a crucial role in the amplification of pyroptosis signals and the enhancement of the body's anti-infection/anti-tumor immune responses." (PMID 39221221, 2024). "Hydrogen is also likely to alleviate tumor volume and weight in the xenograft mouse model through the ROS/NLRP3/caspase-1/GSDMD-mediated pyroptotic pathway." (PMID 39011036, 2024). "The protein expression level of NLRP3, caspase 1, GSDMD, IL-1β and IL-18 in XRZYBXD high dose group were also significantly higher than those in the tumor model group by WB." (PMID 40046008, 2024). "Crucially, several anticancer agents can prompt pyroptosis in tumour cells by stimulating the NLRP3 inflammasome and the subsequent GSDMD pathway." (PMID 38804602, 2024). "The mRNA relative expression level of NLRP3, Caspase 1, GSDMD, IL-1β and IL-18 in XRZYBXD high dose group were significantly higher than those in the tumor model group by Q-PCR." (PMID 40046008, 2024). "Caspase-3 can induce a pyroptosis-like process in tumor cells that are otherwise in the process of apoptosis via gasdermin-E (GSDME), a homologous protein of GSDMD." (PMID 36744134, 2023). "Previous research studies show that GSDMD is required for CD8+ T cell cytotoxicity toward LC cells, and GSDME represses tumor growth in vivo." (PMID 36941988, 2023). "Our data also highlight an unexpected link between GSDMD-mediated pyroptosis and the AMPK signaling pathway in certain tumor cells." (PMID 37495617, 2023). "GSDMD protein levels are dramatically increased in NSCLC, which is correlated with aggressive traits like larger tumor sizes and advanced TNM stages." (PMID 37752941, 2023). "It had been proved that GSDMD was highly expressed in NSCLC tumor tissue, and the level of expression was positively correlated with tumor size and TNM stage." (PMID 37194012, 2023). "For example, GSDMD was found to be upregulated in non-small lung cancer (NSCLC), which promoted tumor metastasis." (PMID 38011122, 2023).